EGFR (epidermal growth factor receptor)
Diseases named in the same sentence as EGFR in open-access papers (continued):
Sharing a sentence is not in itself a finding about the gene and the disease.
pancreatic cancer (continued). "In pancreatic cancer cells, the formation of EGFR/ErbB3 heterodimers are also evidenced to influence the pancreatic cancer cells’ sensitivity to erlotinib." (PMID 30961642, 2019). "Mechanistically, VPA treatment was evidenced to result in significant inactivation of Akt and MAPK signalings via simultaneous down-regulation of EGFR, ErbB2, as well as ErbB3 in pancreatic cancer cells." (PMID 30961642, 2019). "Increased levels of YAP-1 and Epidermal Growth Factor Receptor (EGFR) activation have been previously reported to be compensatory mechanisms to KRAS inhibition in pancreatic cancer cells." (PMID 31451509, 2019). "We demonstrated that VPA inhibits proliferation/survival of pancreatic cancer cells as well as induces caspase-dependent apoptosis selectively in EGFR/ErbB2/ErbB3-coexpressing pancreatic cancer within its clinically achievable range." (PMID 30961642, 2019). "Very recently, alantolactone, a natural sesquiterpene lactone, was shown to down-regulate phospho-STAT3 and enhance EGFR inhibition by erlotinib or afatinib in pancreatic cancer." (PMID 31422383, 2019). "An oncogenic role of hRNase5/ANG in pancreatic cancer through activation EGFR phosphorylation rendered cancer cells more addicted to the EGFR pathway and sensitive to EGFR TKI erlotinib treatment in vitro and in vivo." (PMID 30449278, 2018). "The addition of EGFR TKIs such as erlotinib to gemcitabine demonstrated a significantly higher survival rate in patients diagnosed with pancreatic cancer." (PMID 30326853, 2018). "And the activity of EGFR as a key receptor tyrosine kinase was shown to be regulated by NDRG1 in human pancreatic cancer cells." (PMID 29467385, 2018). "It would be worthwhile to further evaluate hRNase5/ANG as a predictive biomarker for EGFR inhibitor therapy in pancreatic cancer in a systematic way through prospective clinical trials in the future." (PMID 30449278, 2018). "For example, epidermal growth factor receptor (EGFR) has been used to target GNPs into pancreatic cancer cell lines in both in vitro and in xenograft mouse models." (PMID 29558451, 2018). "Although both EGFR signaling and miRNAs can profoundly influence pancreatic cancer cell behavior, the role of miRNAs in EGF-mediated phenotypes is poorly defined." (PMID 30464258, 2018). "This aptamer recognizes EGFR in pancreatic cancer cells and internalizes itself, along with Gem coupled to a polymer, resulting in inhibition of tumor cell proliferation with low toxicity levels." (PMID 29928493, 2018). "By contrast, the blockade of EGFR expression reduces the growth and metastatic potential of pancreatic tumor." (PMID 29596435, 2018). "EGFR is the common cell surface receptor of RNase A and angiogenin to trigger proliferation of pancreatic cancer cells." (PMID 30534052, 2018). "For instances, some inhibitors of the epidermal growth factor receptors (EGFR) were approved by FDA for the treatment of several cancer types including pancreatic cancer." (PMID 30643798, 2018). "The limited benefit of EGFR-targeted therapies in pancreatic cancer calls for identification of potential biomarkers by stratifying patients to predict drug response." (PMID 30449278, 2018). "The theranostics agent can efficiently regulate double-targeted thermochemotherapy against pancreatic tumor, monitor different cellular targeting by MR imaging, and distinguish various EGFR-expressing pancreatic tumor cells." (PMID 29755355, 2018). "It would be of interest to further address the regulatory mechanisms and functions of hRNase5/ANG and EGFR, either autocrine or paracrine in different cells in the pancreatic tumor microenvironment." (PMID 30449278, 2018). "EGFR is commonly over-expressed in pancreatic cancer cells and, thus, we chose the EGFR-STAT3 pathway as the focus our study." (PMID 30400136, 2018). "The overexpression of EGFR among our biomarkers is related to the prognosis of patients with pancreatic cancer." (PMID 30279327, 2018).
pancreatic cancer (continued). "Our immunohistochemical studies on tumors from xenografts showed high EGFR expression in all pancreatic tumors of untreated animals." (PMID 28755527, 2017). "In vivo123I gamma camera imaging revealed high levels of NIS-mediated radionuclide accumulation in pancreatic tumors both at 24 and 48 h after systemic injection of EGFR-targeted LPEI-PEG-GE11/NIS." (PMID 28380420, 2017). "A recent phase 3 trial of EGFR inhibitors has shown to be ineffective, including the use of the monoclonal antibody cetuximab in patients with late‐stage pancreatic cancer." (PMID 28755527, 2017). "Examination of PDAC patient samples has shown upregulated EGFR (ERBB1) in up to 90% of pancreatic tumors." (PMID 28388589, 2017). "EGFR overexpression has been observed in most pancreatic cancer patients and plays prominent roles in malignant transformation, prevention of apoptosis, and drug resistance." (PMID 29262554, 2017). "CHIP-EGFR: EGFR (epidermal growth factor receptor) is the promoter of pancreatic cancer, which can initiate downstream signaling cascade, such as MAPK, PI3K/Akt, and Src pathways." (PMID 28839186, 2017). "This suggests that downregulation of EGFR protein levels is responsible for the growth inhibitory effect of CuB in pancreatic cancer cells." (PMID 29262554, 2017). "EGFR or STAT3 feedback activation in response to MEK inhibitors was also shown to limit efficacy in pancreatic cancer cells." (PMID 29262554, 2017). "It has been previously demonstrated that epidermal growth factor receptor (EGFR) is one of the molecules overexpressed in pancreatic cancer, playing an important role in carcinogenesis." (PMID 28640192, 2017). "Due to a high rate of acquired or inherent resistance, targeting EGFR has proven to be insufficient in effectively treating human pancreatic cancer." (PMID 29262554, 2017). "In this study, we demonstrate for the first time that CuB inhibits pancreatic cancer cell proliferation by interfering with EGFR levels and downstream signaling of PI3K/Akt/mTOR and STAT3." (PMID 29262554, 2017). "The targeted toxin 425(scFv)‐ETA, consisting of an anti‐EGFR single‐chain Fv antibody fused to a truncated Pseudomonas exotoxin, was strongly cytotoxic toward metastatic pancreatic cancer cells (L3.6pl) with an IC50 of 0.1 nm." (PMID 28755527, 2017). "Based on our results, we propose the combination of NGS sequence data with EGFR expression analysis in order to find the most beneficial treatment in pancreatic cancers." (PMID 28957417, 2017). "Sialidase NEU1 has been shown to be involved in epithelial to mesenchymal transition in pancreatic cancer due to activation of matrix metalloproteinase 9-EGFR signaling after reduction of EGFR sialylation." (PMID 28420408, 2017). "Nonetheless FDA approved only three new treatments in the last 20 years for pancreatic cancer (gemcitabine, erlotinib, nab-paclitaxel), of which the only targeted agent is the EGFR inhibitor erlotinib." (PMID 28957417, 2017). "In human pancreatic cancer, the expression level of EGFR is closely related to the prognosis of the disease." (PMID 29018223, 2017). "EGFR signaling is required for oncogenic KRAS-induced pancreatic tumorigenesis, and EGFR signaling activation also induces upregulation of FASN in pancreatic cancer cells in an ERK-dependent manner." (PMID 29295482, 2017). "Nearly 60% of pancreatic cancers demonstrate overexpression of EGFR, and therefore EGFR constitutes a promising therapeutic target." (PMID 29088829, 2017). "Together, our results suggest that periostin regulates the activity of pancreatic cancer cells through EGFR-Akt and EGFR-Erk-c-Myc signaling pathways." (PMID 29163770, 2017). "Our results showed that phosphorylated EGFR increased (fold change 1.28) with the increase of stemness of pancreatic cancer cells treated with gemcitabine." (PMID 29018223, 2017). "In pancreatic cancer, shorter overall survival was found for patients with EGFR staining of the tumor cell cytoplasm." (PMID 28740577, 2017).
pancreatic cancer (continued). "In summary, the present study revealed that gemcitabine-induced HPA1 promoted invasion and metastasis of pancreatic cancer cells via activating EGFR signaling." (PMID 28938567, 2017). "In conclusion, CuB treatment had a strong growth inhibitory effect in pancreatic cancer cells by decreasing EGFR levels and downstream signaling of PI3K/Akt/mTOR and STAT3." (PMID 29262554, 2017). "Such an adjuvant treatment can sensitize chemoresistant pancreatic cancer cells by downregulation of EGFR, Akt, and MAPK dependent pathways, as well as modulation of ROS homeostasis." (PMID 28801576, 2017). "Pre-clinical evidence supports epidermal growth factor receptor (EGFR) involvement in the biology of pancreatic cancer." (PMID 28445400, 2017). "Specific binding of the EGF(scFv)–MAP tau construct to EGFR-overexpressing pancreatic cancer cell line (L3.6pl) was revealed by flow cytometry with the absence of non-specific binding to EGFR− HEK293 cells." (PMID 28653985, 2017). "In summary, in unselected patients with locally advanced or metastatic pancreatic cancer, the addition of EGFR-based therapy to chemotherapy increases toxicity, but does not improve efficacy." (PMID 28445400, 2017). "EGFR overexpression is thought to be related with bad outcome of pancreatic cancer, thus, it is promising to inhibit the EGFR signaling pathway for treatment." (PMID 28839186, 2017). "In PDAC progression the RAC1 GEF VAV1 has been shown to possess a role by acting synergistically with the EGFR to stimulate pancreatic tumor cell proliferation." (PMID 28499439, 2017). "For instance, kaempferol inhibited cell growth and migration of pancreatic cancer through the blockade of epidermal growth factor receptor (EGFR) -related pathway in vitro." (PMID 29137257, 2017). "Combination therapy with MEK and STAT3/EGFR inhibitors has been demonstrated to exert significant anti-pancreatic cancer efficacy." (PMID 29262554, 2017). "The results of the present study demonstrate that CuB treatment alone had strong growth inhibitory effects in pancreatic cancer cells through inhibition of EGFR expression level and activity." (PMID 29262554, 2017). "It was found that a 170 kDa EGFR along with a 65 kDa processed constituent (of C-terminal) is released in exosomes from the pancreatic cancer cells." (PMID 27999198, 2017). "Integrin α6β4 is highly expressed in pancreatic carcinoma and contributes to cancer progression, in part, through the specific DNA demethylation and upregulation of epidermal growth factor receptor (EGFR) ligands amphiregulin (AREG) and epiregulin (EREG)." (PMID 28733611, 2017). "Cytotoxicity was therefore evaluated in EGFR‐overexpressing human pancreatic carcinoma cells (BxPC‐3 and MIA PaCa‐2)." (PMID 28755527, 2017). "In this context, VEGF antibodies, tyrosine kinase inhibitors, or EGFR antibodies have been discussed for the treatment of advanced pancreatic carcinoma." (PMID 28774282, 2017). "Our study is the first to verify the feedback loop between PIM-1 and the EGFR signalling pathway in pancreatic cancer." (PMID 27596051, 2016). "Although gemcitabine is a key adjuvant chemotherapy agent for advanced pancreatic cancer, the combination of agents targeting EGFR and gemcitabine has been shown to be superior to gemcitabine alone." (PMID 27399694, 2016). "Previous reports have shown that increased EGFR expression has been found in human pancreatic cancer tissue and correlated with a poor prognosis." (PMID 27596051, 2016). "Increased expression of EGFR expression with TGFα found upregulated in pancreatic cancer, ovarian cancer, Wilms tumor and other tissues, both of which were positively correlated." (PMID 26843615, 2016). "In conclusion, PIM-1 and the EGFR pathway form a feedback loop, which contributes to the malignancy of pancreatic cancer." (PMID 27596051, 2016).
pancreatic cancer (continued). "This study evaluated the prognostic significance of human epidermal growth factor receptor (HER) family members (HER1–4) expression in patients with operable pancreatic cancer." (PMID 27871278, 2016). "EGFR and HGFR are representative receptor tyrosine kinases that are critical causes of aggressively malignant pancreatic cancers." (PMID 27175782, 2016). "The fact that these in vitro characteristics were also evident in an in vivo environment provides stronger evidence for the use of DIM in patients with pancreatic cancer exhibiting overexpression of EGFR and NF-κB." (PMID 27447608, 2016). "We propose that AGR2-induced EGFR signaling is a common and essential link between injury-induced tissue regeneration and the development of pancreatic cancer." (PMID 27764193, 2016). "To evaluate the effects of PA-MSHA on EGFR signaling in pancreatic cancer cells, we examined the expression of key downstream proteins in the EGFR pathway (t-EGFR, t-AKT, t-ERK, p-EGFR, p-AKT, and p-ERK) by western blotting." (PMID 27788491, 2016). "It co-localizes and physically associates with activated EGFR; thus leading to AP1 transcriptional activity and effectively promotes migration in pancreatic cancer cells." (PMID 27196083, 2016). "Upregulated EGFR is also found in pancreatic cancer tumors, which correlate with a dismal prognosis." (PMID 27175782, 2016). "Consistent with some recent studies, we showed that the rate of EGFR expression was 45.4% among the pancreatic cancer patients, as tested by a total of 357 patients with pancreatic carcinoma." (PMID 27399694, 2016). "Based on those previous studies, EGFR and the related pathway had shown an important role in pancreatic cancer." (PMID 27399694, 2016). "We have previously shown that EGFR-related signaling pathway is of vital importance for migratory activity of pancreatic cancer cells." (PMID 27175782, 2016). "Subsequent studies from this group suggest that the role of Nrf2 in pancreatic cancer involves Nrf2-mediated changes in EGFR signaling." (PMID 27754368, 2016). "Treatment of kaempferol, which was administered exogenously to pancreatic cancer cells, significantly decreased the phosphoylation levels of EGFR, Src, AKT, and ERK1/2 in a time-dependent manner in Miapaca-2 and Panc-1 cells." (PMID 27175782, 2016). "Additional studies are necessary to elucidate the potential mechanisms of the effects of EGFR on tumorigenesis and the significance of EGFR in the treatment of human pancreatic cancer." (PMID 27399694, 2016). "EMT has been observed in tumor samples from patients with non-small cell lung cancer (NSCLC) that developed resistance to epidermal growth factor receptor inhibitors, and with pancreatic cancer that developed resistance to gemcitabine." (PMID 26527679, 2016). "In pancreatic cancer tissues, EGFR was highly expressed and positively correlated with HAb18G/CD147." (PMID 27556697, 2016). "In this study, we investigated the nature of kaempferol’s anti-cancer impact on human pancreatic cancer cell lines through the blockade of EGFR-related intracellular signaling." (PMID 27175782, 2016). "A molecular organizational G protein-coupled receptor (GPCR)-signaling platform was uncovered by us that was deemed essential for the activation of EGFR and its targeted translation in pancreatic cancer." (PMID 27029067, 2016). "Recent studies have also defined an essential role for EGFR in the early pathogenesis of pancreatic cancer." (PMID 27764193, 2016). "Inhibiting EGFR signaling has also been reported to improve the efficacy of gemcitabine in human pancreatic tumor xenograft models." (PMID 27556697, 2016).
pancreatic cancer (continued). "In pancreatic cancer tissues, high HAb18G/CD147 expression was significantly correlated with high EGFR expression, and high expression of both HAb18G/CD147 and EGFR was observed in 71.57% of pancreatic cancer samples." (PMID 27556697, 2016). "Enhanced AGR2 expression and EGFR signaling are also universally present in human pancreatic cancer, which support a linkage between tissue injury, regeneration, and cancer pathogenesis." (PMID 27764193, 2016). "EGFR overexpression and/or enhanced activity has been reported in many solid tumors including pancreatic cancer." (PMID 27788491, 2016). "EGFR mRNA levels in pancreatic tumor tissues increased 2.33-fold on average compared to those in adjacent non-tumor tissues (P = 0.0973, n = 7)." (PMID 27556697, 2016). "Mutation, amplification, or overexpression of the prototype member, EGFR (HER1/ErbB), occurs in breast, lung, bladder, head-and-neck, and pancreatic cancers." (PMID 27153091, 2016). "Our previous work demonstrated that CHIP ubiquitinated EGFR for proteasome-mediated degradation in pancreatic cancer cells and suppressed EGFR downstream signaling pathways." (PMID 27007160, 2016). "In human pancreatic cancer, high EGFR expression is required for both the initiation and survival of ADM (and pancreatic intraepithelial neoplasia [PanIN]) lesions, and EGFR ablation restricts the development of PDAC." (PMID 27556697, 2016). "Ninety-percent of pancreatic cancers, which have a 5-year survival rate of less than 5%, display overexpression of EGFR or the EGFR ligands TGFα and EGF." (PMID 27153091, 2016). "The data regarding the prognostic significance of EGFR (epidermal growth factor receptor) expression and adjuvant therapy in patients with resected pancreatic cancer are insufficient." (PMID 27399694, 2016). "Therapeutic targeting EGFR and its inhibition can cause a reversal of EMT in human pancreatic cancer." (PMID 27029067, 2016). "Epidermal growth factor (EGF) is upregulated in approximately 60% of adenocarcinomas of the pancreas, providing a rationale for the use of EGFR inhibitors in pancreatic carcinoma." (PMID 27438140, 2016). "EGFR overexpression is known to play a pivotal role in many cancer types including pancreatic carcinoma." (PMID 27655713, 2016). "Rash was more frequent with erlotinib plus gemcitabine than with gemcitabine alone, and we observed the association between rash and a better outcome that has been seen in other pancreatic cancer studies of EGFR inhibitors." (PMID 26046796, 2015). "Malignant primary brain tumor and pancreatic cancer are two well-known examples of malignant tumors resistant to conventional therapies where aberrant EGFR-mediated and NF-κB signal transduction pathways are likely to play an important role." (PMID 26480820, 2015). "The concurrent inhibition of cyclooxygenase-2 and EGFR leads to greater anti-tumor activity in pancreatic cancer." (PMID 26429877, 2015). "This stromal protein has been very recently shown to positively correlate with prolonged survival after tumor resection in in pancreatic ductal adenocarcinomas, due to its limiting role in EGFR-expressing pancreatic cancer progression." (PMID 26188123, 2015). "In conclusion, our studies will enhance the translational acquaintance of pan-EGFR inhibitors for combinational therapies to combat against lethal pancreatic cancer." (PMID 25686822, 2015). "Pancreatic cancer cells are known to depend on EGFR signaling, and therapies targeting this signaling pathway are under evaluation in the clinic." (PMID 26053043, 2015). "Overall, we report evidence that D11 treatment induces cell death and inhibits signaling pathways deregulated in brain and pancreatic cancer cells, notably, the EGFR and NF-κB signaling cascades." (PMID 26480820, 2015). "With the aim of optimizing therapeutic strategies, EGFR expression in pancreatic tumors has been determined in some clinical trials in order to assess its potential role in predicting treatment efficacy." (PMID 25918250, 2015).